PMEPA1 (prostate transmembrane protein, androgen induced 1)
Diseases named in the same sentence as PMEPA1 in open-access papers (continued):
Sharing a sentence is not in itself a finding about the gene and the disease.
breast carcinoma (18 papers, 2014 to 2026). "PMEPA1 encodes the androgen-induced prostate transmembrane protein 1 and is highly regulated in prostate cancer, lung cancer, and breast cancer." (PMID 37987362, 2023). "Knockout of PMEPA1 (isoform -a) also led to reduction of xenograft growth and lung metastasis of breast cancer cells, which was associated with downregulation of vascular endothelial growth factor alpha (VEGFA) and interleukin-8 (IL8)." (PMID 32842649, 2020). "Frame-shift, in-frame, missense and non-sense deletions were found in 22 different type of mutations (includes 6 duplicate mutations) for PMEPA1 in breast cancer." (PMID 30760814, 2019). "Previous work showed that the elimination of PMEPA1 in breast cancer cells significantly decreased their ability to form spheroids in Hs578t and BT-549 cells." (PMID 37987362, 2023). "Loss of PMEPA1 (isoform -a) reduced TGF-β–induced growth and motility in breast cancer cells, and inhibited breast tumor xenograft growth with increased expression of PTEN and moderate phosphorylation of Akt." (PMID 32842649, 2020). "It was noted that overexpression of PMEPA1 (isoform -a) was detected in multiple solid tumors including breast cancer, colon cancer, renal cancer, stomach cancer, rectal adenocarcinomas, pancreatic endometrial and prostatic adenocarcinomas." (PMID 32842649, 2020). "Earlier studies from our laboratory showed that breast cancer cells escape TGF-β mediated growth inhibition by overexpressing transmembrane prostate androgen induced (TMEPAI/PMEPA1), a direct target gene of Smad-dependent TGF-β signaling." (PMID 31798766, 2019). "A negative correlation existed between EZH2 and its targets except in PMEPA1, which showed a weak positive correlation in breast cancer cell lines." (PMID 30760814, 2019). "NF-KappaB Interacting LncRNA (NKILA), encoded by a gene at chromosome 20q13 just near by the prostate transmembrane protein androgen induced 1 (PMEPA1) (also named solid tumor associated gene 1, STAG1), is upregulated by NF-κB in breast cancer." (PMID 28412955, 2017). "PMEPA1 could inhibit canonical Smad signalling by reducing phosphatase and tensin homolog in breast cancer." (PMID 34254950, 2021). "In breast cancer cells, PMEPA1 could be upregulated by classical TGF-β/Smad signaling pathway, and silencing of PMEPA1 significantly could inhibit the migration ability of MDA-MB-231 cells and promoted the process of EMT." (PMID 28511643, 2017). "High expression of PMEPA1 (isoform -a) was detected in estrogen receptor/progesterone receptor–negative and human epidermal growth factor receptor-2–negative breast cancer cell lines and primary breast cancers and this expression is increased by TGF-β treatment." (PMID 32842649, 2020). "Upon EZH2 knockdown, fold change in the target gene expression for GPNMB, CoL5A1, POMT2, PMEPA1, VGLL4 and SUMF1 was found to be 1.3, 2.8, 2.2, 2, 1.7 and 1.8, respectively in MCF-7 breast carcinoma cells as detected by qPCR." (PMID 30760814, 2019). "A concomitant improved relapse free survival in breast cancer patients with increased expression of POMT2, PMEPA1 and SUMF1 indicated their tumor suppressive behavior." (PMID 30760814, 2019). "KM plotter analysis showed improved relapse-free survival with increased expression of PMEPA1, POMT2, VGLL4 and SUMF1 in breast cancer patients indicating their therapeutic potential." (PMID 30760814, 2019). "In qRT-PCR data obtained from MCF-7, T47D, MDA-MB-231 and MDA-MB-453 breast cancer cell lines, a negative correlation was observed between EZH2 and its target gene expression except for PMEPA1 that shared a weak positive correlation with EZH2." (PMID 30760814, 2019).
lung carcinoma (10 papers, 2014 to 2024). "A study conducted in human lung cancer cells revealed that PMEPA1 contributes to TGF-β-induced EMT by the downregulation of insulin receptor substrate-1 (IRS-1) and the production of reactive oxygen species (ROS)." (PMID 38173834, 2023). "PMEPA1 expression was distinctly increased in many types of cancers, like colorectal carcinoma, pancreatic carcinoma, and lung carcinoma." (PMID 35497877, 2022). "Using Integrative Genomics Viewer, genome browser plots of the 5hmC locus located in PLEKHA6 and PMEPA1 were illustrated in both lung cancer patients and healthy controls." (PMID 35073982, 2022). "Silencing of PMEPA1(isoform -d) in lung cancer Calu3 and NCI-H2 cells dramatically inhibited the cell growth in vitro and subcutaneous tumor formation in vivo through enhanced Smad2 phosphorylation in TGF-β dependent way." (PMID 32842649, 2020). "PMEPA1 was found highly expressed in the lung cancer cell lines,whereas knockdown of PMEPA1 could significantly inhibit the proliferation of cancercells.Overexpression of PMEPA1 was associated with poor prognosis of lung cancer, whichwas in line with our findings." (PMID 33196759, 2020). "PMEPA1 (isoform -a and -d) was also reported to promote the proliferation of A549 lung cancer cells." (PMID 32842649, 2020). "Previous studies also showed that PMEPA1 can regulate EMT in lung cancer cells by modulating the ROS and IRS-1 signaling pathways." (PMID 28511643, 2017). "Further, immunofluorescence staining of F-actin showed that PMEPA1 silencing could lead to a decrease in F-actin reorganization during EMT in lung cancer cells." (PMID 38173834, 2023).
colorectal cancer (7 papers, 2012 to 2025). A primary or metastatic malignant neoplasm that affects the colon or rectum. "Although the conclusion needs more clinical studies to valid, PMEPA1 might has the potential to serve as a meaningful biomarker for high‐risk CRC or to serve as a therapeutic target for intervene colorectal cancer." (PMID 30887697, 2019). "We speculated that the tissue or organ specific expression of PMEPA1 might cause the contradictory phenotype in colorectal cancer." (PMID 30887697, 2019). "High levels of PMEPA1 protein have been observed in various tumor types, including prostate, bladder, colorectal cancers, and glioblastoma." (PMID 40649997, 2025). "The expression of PMEPA1 was discovered to be distinctly increased in colorectal cancer, and its upregulation in tumor cells was related to EMT progress via regulating TGF-β signaling resulting." (PMID 35497877, 2022). "Prostate transmembrane protein androgen induced 1 (PMEPA1) has been shown to regulate the transforming growth factor-β signaling pathway to induce EMT in colorectal cancer cells, consequently promoting the occurrence of metastasis." (PMID 33397428, 2021). "We furthermore demonstrated PMEPA1 promotes colorectal cancer metastasis and EMT in vivo and in vitro." (PMID 30887697, 2019). "We then tested mRNA and protein level of PMEPA1 by RT‐PCR and Western blot, we investigated the influence on colorectal cancer cells with the comparison of relative control cell lines." (PMID 30887697, 2019). "To investigate the molecular role of PMEPA1 in colorectal cancer cells, first, we detected the mRNA and protein level in several colorectal cancer cell lines by RT‐PCR and Western blot." (PMID 30887697, 2019). "These new findings have thrown light on the role of PMEPA1 in colorectal cancer." (PMID 30887697, 2019). "PMEPA1 promotes EMT-mediated metastasis by activating TGF-β non-classical signal cascades in colorectal cancer." (PMID 35668494, 2022). "We found that PMEPA1 activates the bone morphogenetic proteins (BMP) signalling of TGF‐β signalling resulting in promoting EMT and accelerating the proliferation and metastasis of colorectal cancer." (PMID 30887697, 2019). "However, the relationship between PMEPA1 and EMT in colorectal cancer metastasis is still poorly understood." (PMID 30887697, 2019). "In the colorectal cancer, PMEPA1 promoted EMT via targeting the non-canonical TGF-beta signalling." (PMID 34254950, 2021).
triple-negative breast carcinoma (6 papers, 2014 to 2024). An invasive breast carcinoma which is negative for expression of estrogen receptor (ER), progesterone receptor (PR), and human epidermal growth factor receptor 2 (HER2). "A study examining the role of adriamycin in triple-negative breast cancer cells (TNBC) suggested that PMEPA1-positive cells had a higher phosphorylation profile of PI3K and AKT." (PMID 38173834, 2023). "Another study conducted in triple-negative breast cancer tumor samples reported that PMEPA1 knockdown reduced Snail levels and inhibited cell migration, invasion, and metastasis both in vitro and in vivo." (PMID 38173834, 2023). "The triple negative breast cancer patients with higher TMEPAI/PMEPA1 and lower Smad2 mRNA expression showed decreased survival." (PMID 31798766, 2019). "Moreover, a study on triple-negative breast cancer reported that knocking down PMEPA1 increased p27 expression." (PMID 39607204, 2024). "It has been reported that PMEPA1 could exacerbate triple-negative breast cancer (TNBC) tumor progression by increasing PTEN turnover and attenuating PTEN expression to promote the expression of atypical PI3K/AKT signaling." (PMID 38173834, 2023). "TMEPAI/PMEPA1 is known to be highly expressed in various types of cancer, including triple-negative breast cancer (TNBC)." (PMID 34638419, 2021).
bladder cancer (5 papers, 2021 to 2025). "High expression of PMEPA1 was associated with poor prognosis of bladder cancer patients." (PMID 38385084, 2024). "METTL16 inhibits the proliferation and cisplatin resistance of bladder cancer by degrading PMEPA1 mRNA in the m6A manner through the autophagy pathway." (PMID 41194259, 2025). "To summarize, PMEPA1 promotes bladder cancer cell malignancy including cell growth, colony formation, cell migration, and invasion abilities." (PMID 34777336, 2021). "We then tested the protein level of PMEPA1 by Western blot, and we investigated the influence on bladder cancer cells with the comparison of relative control cell lines." (PMID 34777336, 2021). "Prostate transmembrane protein androgen induced 1 (PMEPA1) has been reported to promote cancer progression, but the potential role of PMEPA1 in bladder cancer (BLCA) remains elusive." (PMID 34777336, 2021). "To investigate the role of PMEPA1 in bladder cancer, firstly, we selected cell lines, T24 and 647-V for building the stable PMEPA1 knockdown and overexpression cell lines." (PMID 34777336, 2021). "This indicated that PMEPA1 may be a potential biomarker for predicting the progression and prognosis of bladder cancer." (PMID 38385084, 2024). "METTL16, by binding to the m6A site of the 3' end of prostate transmembrane protein androgen-induced protein 1 (PMEPA1), reduces its mRNA stability, thus inhibiting the proliferation of bladder cancer cells and increasing sensitivity to cisplatin, mediated by the autophagy pathway." (PMID 39155349, 2024). "In addition, they also provided evidences that knockout of PMEPA1 remarkably repressed the growth and metastasis and correlated with cell malignancy and the tumor microenvironment in bladder cancer." (PMID 35497877, 2022). "Besides, CCK-8 and colony formation analysis showed that the increased proliferation of bladder cancer cell lines induced by METTL16 knockdown could be reversed by interference with PMEPA1." (PMID 38385084, 2024). "In addition, METTL16 reduced the mRNA stability of prostate transmembrane protein androgen induced-1 (PMEPA1) via binding to its m6A site in the 3'-UTR, thereby inhibited the proliferation of bladder cancer cells and increased the sensitivity of cisplatin through PMEPA1-mediated autophagy pathway." (PMID 38385084, 2024). "In addition, PMEPA1 was also shown to promote bladder cancer in TMA." (PMID 38385084, 2024). "In addition, a previous study reported that PMEPA1 expression was distinctly upregulated in bladder cancer, and clinical studies revealed that it may be a new marker in predicting tumor progression and clinical outcome." (PMID 35497877, 2022). "Moreover, in vitro study revealed that PMEPA1 promotes bladder cancer cell malignancy." (PMID 34777336, 2021). "Together, knocking down PMEPA1 reversed the proliferation and cisplatin-resistance induced by METTL16 knockdown through autophagy pathway in bladder cancer cells." (PMID 38385084, 2024). "Our finding indicated that PMEPA1 and METTL16 have co-localization in bladder cancer cells." (PMID 38385084, 2024). "Further research had also shown that in bladder cancer cells, METTL16 could specifically recognize the m6A sites of the 3'-UTR in PMEPA1 mRNA, which decreased the stability of PMEPA1 mRNA and eventually led to a decrease in the protein level of PMEPA1 in an m6A-dependent manner." (PMID 38385084, 2024). "Moreover, METTL16 significantly inhibited bladder cancer cell proliferation and sensitized bladder cancer cells to cisplatin in vitro and in vivo via HIF-2α-PMEPA1-autophagy axis in a m6A manner, which might provide fresh insights into bladder cancer therapy." (PMID 38385084, 2024).
pancreatic cancer (5 papers, 2019 to 2025). "Some researches indicate that PMEPA1 inhibits the proliferation, invasion and migration of pancreatic cancer cells by activating the PTEN/PI3K/AKT pathway." (PMID 35783291, 2022). "Additionally, it has been reported that PMEPA1 interference enhanced GEM-sensitivity in human pancreatic cancer cells." (PMID 41209344, 2025).
prostate tumor (5 papers, 2015 to 2025). "Quantitative-PCR (Q-PCR) analysis in matched prostate normal/tumor tissues showed that decreased expression of PMEPA1 in approximately 65% of prostate tumors, which also strongly associated with higher pathologic stage and serum prostate-specific antigen (PSA)." (PMID 32064040, 2020). "Xu and his group reported that the expression of PMEPA1 was evidently increased in prostate tumor, and its silence repressed the proliferation and metastasis of prostate tumor cells via modulating the ubiquitin-proteasome pathway." (PMID 35497877, 2022). "Taken together, our findings first time defined the prostate tumorigenesis mediated by PMEPA1-d and -e isoforms, providing novel insights into the new strategies for prognostic evaluation and therapeutics of prostate tumor." (PMID 32064040, 2020). "The PMEPA1 silencing conferred the development of resistance to AR inhibitors in vitro, as well as promoted the androgen independent xenograft growth of prostate tumor in nude mice." (PMID 32064040, 2020). "The Cancer Genome Atlas (TCGA) data analysis further validated the biomarker potential of PMEPA1 isoforms for prostate tumor progressions." (PMID 32842649, 2020). "Initial evaluations of PMEPA1 mRNA expression in matched normal and prostate tumor specimens suggested decreased expression of PMEPA1 in two-third of CaP patients." (PMID 25883222, 2015). "In contrast, the expression of PMEPA1-a isoform was not altered significantly in prostate tumor compare to benign prostate." (PMID 32842649, 2020). "Here, we focused on defining the expressions, regulations and biological behaviors/functions of understudied PMEPA1 isoforms (d and e) in the context of both androgen and TGF-β signaling, and further exploration of the clinical significances and relevance of these isoforms in prostate tumor." (PMID 32064040, 2020). "All these findings explicitly outlined newly discovered PMEPA1-e isoform as a gene promoting prostate tumor growth without manipulating classic androgen and TGF-β signaling in prostate tumorigenesis, and the cell growth promoting mechanism of PMEPA1-e needed further elucidation." (PMID 32064040, 2020).
esophageal squamous cell carcinoma (4 papers, 2021 to 2023). Esophageal squamous cell carcinoma (ESCC) is a type of esophageal carcinoma (EC) that can affect any part of the esophagus, but is usually located in the upper or middle third. "LINC00941 promotes the progression of esophageal squamous cell carcinoma by regulating PMEPA1 expression as a competitive endogenous RNA of mir-877-3p." (PMID 35647035, 2022). "Moreover, the miR-877-3p/PMEPA1 axis plays a vital role in accelerating esophageal squamous cell carcinoma (ESCC) cell proliferation, metastasis, and EMT in esophageal cancer." (PMID 38173834, 2023). "A novel linc00941 was identified in esophageal squamous cell carcinoma (ESCC), which was suggested to be a competing endogenous RNA by bioinformatics prediction and tests for miR-877-3p, which targeted the 3’ UTR of PMEPA1, thereby inhibiting PMEPA1 expression." (PMID 38173834, 2023).
melanoma (4 papers, 2019 to 2026). A malignant, usually aggressive tumor composed of atypical, neoplastic melanocytes. "PMEPA1 protein regulates TGF-β, and although its role in melanoma is complex, it is generally considered to promote tumor progression." (PMID 39695652, 2024). "Furthermore, in melanoma cells CSDE1 interacts with AGO2 in the miRISC complex and counteracts the silencing of PMEPA1 mRNA by miR-129-5p." (PMID 38600987, 2024). "Similarly, to promote melanoma cell aggressiveness CSDE1 downregulates the levels of PTEN mRNA, while it upregulates the levels of PTPN2 and PMEPA1 mRNAs." (PMID 38600987, 2024).
ovarian cancer (4 papers, 2014 to 2023). A primary or metastatic malignant neoplasm involving the ovary. "It was soon followed by the documentation of the expression and functional analysis of transmembrane prostate androgen-induced protein (TMEPAI)/PMEPA1 in other solid tumors including renal, colon, breast, lung, and ovarian cancers." (PMID 32842649, 2020). "We have demonstrated that PMEPA1 is a COX-2, PGE2, PGF2α, and calcium (through Ionophore treatment) -induced gene in colon and ovary cancer cells." (PMID 32410997, 2020).
colon cancer (3 papers, 2016 to 2023). "If this also happens in colon cancer cells, they would have to reduce PMEPA1 levels before invading blood vessels and releasing CTCs." (PMID 35153760, 2021).
asthma (2 papers, 2021 to 2022). "Significant DMPs fall within genes involved in the TFG-β related pathways (e.g. BMP2, FLCN, ING2, PMEPA1, PRDM16, TGFB1I1 and TGFBR3), in line with previous studies that reported an association between these genes and the increased asthma risk." (PMID 35619695, 2022). "Moreover, it has been evidenced to be associated with protein expression levels of PMEPA1, a negative regulator of the activity of transforming growth factor β (TGF-β), which has been widely proposed to play a key role in allergy and asthma pathophysiology." (PMID 34442380, 2021).
gastric cancer (2 papers, 2024). A primary or metastatic malignant neoplasm involving the stomach. "In the TCGA database, the expression level of PMEPA1 was elevated in gastric cancer tissues compared with normal tissues in both the paired and unpaired cohorts." (PMID 39607204, 2024). "In our study, sh-PMEPA1-induced G2/M arrest in gastric cancer cells was reversed by 14-3-3σ knockdown." (PMID 39607204, 2024). "This indicates that PMEPA1 bound to 14-3-3σ, promoting its ubiquitination and subsequent degradation through the ubiquitin-proteasome pathway in gastric cancer cells." (PMID 39607204, 2024). "Our findings underscored the critical role of PMEPA1 in the cell cycle, thus influencing gastric cancer cell proliferation." (PMID 39607204, 2024). "When PMEPA1 is knocked down, 14-3-3σ ubiquitination decreases, leading to an increase in the 14-3-3σ protein level and inducing G2/M arrest in gastric cancer cells." (PMID 39607204, 2024). "Although PMEPA1 has been previously reported to promote the development of various tumors, its effects on the growth of gastric cancer, especially its influence on the cell cycle, remain unclear." (PMID 39607204, 2024). "In summary, these results suggested that PMEPA1 recruited TTC3, allowing it to bind 14-3-3σ and promote its ubiquitin-mediated degradation in gastric cancer cells." (PMID 39607204, 2024). "Hence, whether PMEPA1 recruited TTC3 to bind to 14-3-3σ in gastric cancer cells was investigated." (PMID 39607204, 2024).